RPS26P15 (ribosomal protein S26 pseudogene 15)
Gene: Processed pseudogene on chromosome 1 (58,056,133 to 58,056,480, reverse strand). Ensembl gene ENSG00000223416.
Diseases named in the same sentence as RPS26P15 in open-access papers:
RPS26P15 is named in the same sentence as 2 diseases in open-access papers, as found by Europe PMC text mining. Sharing a sentence is not in itself a finding about the gene and the disease. The quoted sentences say what the papers report.
ovarian carcinoma (1 paper, 2019). A malignant neoplasm originating from the surface ovarian epithelium. "All these findings indicated that RPS26P15, AC004057.1, RPS26P31, RPS26P6, RPS26P3 and RPS26P47 were the most potential pseudogenes in regulating hsa-miR-363-3p in ovarian cancer." (PMID 31794425, 2019). "Among 56 predicted pseudogenes, only 6 pseudogenes (RPS26P15, AC004057.1, RPS26P31, RPS26P6, RPS26P3 and RPS26P47) were significantly upregulated in cancer samples (compared to normal samples) and advanced stage of ovarian cancer (compared to early stage ovarian cancer)." (PMID 31794425, 2019).
cancer (1 paper, 2019). A tumor composed of atypical neoplastic, often pleomorphic cells that invade other tissues. "Finally, only 6 pseudogenes, RPS26P15, AC004057.1, RPS26P31, RPS26P6, RPS26P3 and RPS26P47 were significantly upregulated in cancer tissues when compared with normal controls." (PMID 31794425, 2019).